PIEZO2 (piezo type mechanosensitive ion channel component 2)
Diseases named in the same sentence as PIEZO2 in open-access papers (continued):
Sharing a sentence is not in itself a finding about the gene and the disease.
breast carcinoma (continued). "All these results together provide plenitudinous evidence that PIEZO2, downregulated by five oncogenic miRNAs (miR-130b-3p, miR-196a-3p, miR-301a-3p, miR-421 and miR-454-3p), might promote survival and progression of breast cancer by decreasing expression of CDON." (PMID 31058608, 2019). "ANGPTL4, PIEZO2, SCNN1A, LTBP1, and SerpinB2 promote the survival of breast cancer cells in the brain microenvironment." (PMID 37108248, 2023). "Piezo2 knockdown decreases the invasion of MDA-MB-231-BrM2 cells, which metastasize cells from breast cancer to the brain." (PMID 33806911, 2021). "By analyzing expression profile of PIEZO2 using the HPA database, we found that breast cancer was the most suitable candidate for further investigation." (PMID 31058608, 2019). "The Human Protein Atlas indicates immunohistochemical expression in benign and malignant tissues, considering PIEZO2 as not prognostic in breast cancer." (PMID 39001475, 2024). "PIEZO2 expression was not correlated with overall survival in whole breast cancer patients." (PMID 36077309, 2022). "Moreover, the role of PIEZO2 expression in the development and progression of breast cancer has not been identified." (PMID 31058608, 2019). "The data obtained also revealed a favorable prognosis of Piezo2 expression mainly in ER-positive or HER2-negative breast cancer, but a poor prognosis in patients with low expression of Piezo2, suggesting that low expression of Piezo2 might be a potential prognostic biomarker in breast cancer." (PMID 32635333, 2020). "Therefore, we did not see any conclusive evidence that PIEZO2 regulates YAP/TAZ signaling in MDA-MB-231 and BT549 breast cancer cells." (PMID 36077309, 2022).
scoliosis (10 papers, 2018 to 2025). A congenital or acquired spinal deformity characterized by lateral curvature of the spine. "Homozygous individuals for mutations inactivating PIEZO2 suffered from arthrogryposis and scoliosis, whereas carriers of gain‐of‐function mutations were susceptible to multiple congenital contractures of limbs and variable absence of cruciate knee ligaments." (PMID 40965274, 2025). "Previous studies reported null variants of PIEZO2 in 3 families and 2 patients with neuromuscular symptoms and progressive scoliosis, indicating a connection between mechanosensory defects and development of spinal curvature." (PMID 37962965, 2024). "Mutations in human PIEZO2, encoding for a mechanosensitive ion channel, lead to skeletal abnormalities including scoliosis and hip dysplasia." (PMID 32576830, 2020). "A recent report suggests that mutations in the human PIEZO2 gene result in a complex musculoskeletal phenotype involving scoliosis, hip dysplasia and hand deformities." (PMID 32576830, 2020). "In humans, mutations in the PIEZO2 gene, which encodes for a mechanosensitive ion channel, were found to result in skeletal abnormalities including scoliosis and hip dysplasia." (PMID 32576830, 2020). "Recent studies have discovered that biallelic loss-of-function (LoF) mutations in PIEZO2 cause muscular atrophy with perinatal respiratory distress, arthrogryposis, scoliosis and proprioception defects." (PMID 30285720, 2018). "Second, the mutation of the mechanosensitive cation channels Piezo2 may be responsible for symptoms of scoliosis." (PMID 33628392, 2021). "Loss of piezo-type mechanosensitive ion channel component 2 (Piezo2), another well-described mechanoreceptor, in proprioceptive neurons produces a scoliosis-like deformity in mouse." (PMID 40888060, 2025). "The patient’s specific finding has not been seen in the literature; his features do seem consistent with autosomal recessive PIEZO2-related disorder, such as scoliosis, short stature, neonatal hypotonia, and muscle weakness." (PMID 41531622, 2025). "By P60, some of the Piezo2 cKO mice developed scoliosis in addition to the kyphosis." (PMID 32576830, 2020). "Apart from a non-penetrant scoliosis or occasional growth retardation, especially in Piezo2R2756K/R2756K mice, the Piezo2 knock-in mice appeared largely healthy, with no obvious motor deficits." (PMID 38984717, 2024). "Conversely, mice lacking Piezo2 in proprioceptive neurons acquire scoliosis and hip dysplasia, suggesting a nonautonomous role for Piezo2 in regulation of spine alignment and joint integrity." (PMID 32576830, 2020).
amyotrophic lateral sclerosis (8 papers, 2020 to 2025). Amyotrophic lateral sclerosis (ALS) is a neurodegenerative disease characterized by progressive muscular paralysis reflecting degeneration of motor neurons in the primary motor cortex, corticospinal tracts, brainstem and spinal cord. "The irreversible form of this autonomously acquired Piezo2 ion channel microdamage, in association with genetic predisposition and/or environmental risk factors, is suggested to lead to progressive motoneuron death in addition to loss of pain sensation in amyotrophic lateral sclerosis." (PMID 39941012, 2025). "Moreover, the same irreversible microdamage-induced loss of the Piezo2-initiated ultradian muscle spindle-hippocampal and cerebellum-hippocampal axes may lead to amyotrophic lateral sclerosis and Parkinson's disease initiation, respectively." (PMID 40806339, 2025). "Irreversible proprioceptive terminal Piezo2 microinjury is also suggested in a lethal motoneuron disease called amyotrophic lateral sclerosis (ALS), and the autonomic impairment in this condition has long been reported." (PMID 37108199, 2023).
glioma (7 papers, 2016 to 2025). A benign or malignant brain and spinal cord tumor that arises from glial cells (astrocytes, oligodendrocytes, ependymal cells). "PIEZO2 is highly expressed in glioma endothelial cells, where it mediates Ca2+ influx and subsequently promotes the expression and secretion of Wnt11." (PMID 41327436, 2025). "Suggested that Piezo2 expression was elevated in glioma tumor cells, and Piezo2 downregulation inhibited the proliferative capacity of tumor cells and reduced tumor angiogenesis." (PMID 35991548, 2022). "Summarizing, this study supports pieces of evidence for Piezo2 as a crucial regulator of tumor angiogenesis in glioma." (PMID 32635333, 2020). "Recently, Piezo2 has been identified as a critical player in the progression of glioma, supporting cancer cell behavior and angiogenesis." (PMID 32635333, 2020). "Knocking down Piezo2 with a selective small interfering RNA (siRNA) reduced glioma angiogenesis and normalized tumor neovessels." (PMID 29324706, 2018). "More recently, Piezo2 was found to be up-regulated in T-ECs from mouse xenografted with GL261 glioma cells." (PMID 29324706, 2018). "GL261 glioma cells transfected with scrambled shRNA or Piezo2 shRNA were injected subcutaneously into the right flank of nude mice." (PMID 27329839, 2016). "Here, we showed that Piezo2 knockdown led to decreased glioma angiogenesis and reduced vascular hyperpermeability." (PMID 27329839, 2016). "Likewise, Piezo2 was found to be upregulated in a glioma xenograft model, and its depletion reduced glioma angiogenesis." (PMID 37762011, 2023). "Piezo2 is also a crucial regulator of glioma cell growth, migration and invasion." (PMID 36158191, 2022). "Furthermore, in vitro experiments confirmed that Piezo2 down-regulation in endothelial cells resulted in the inhibition of glioma tumor cell growth, migration, and invasion." (PMID 32635333, 2020). "In this study, we investigated the role of Piezo2 in glioma tumor progression." (PMID 27329839, 2016). "Moreover, In vitro co-culture system assay showed that Piezo2 knockdown in endothelial cells suppressed cell proliferation, migration, and invasion of glioma tumor cells." (PMID 27329839, 2016). "Furthermore, PIEZO2 knockdown in endothelial cells has similar inhibitory effects on cellular proliferation and motility but also attenuates the invasive capacity of cocultured glioma tumor cells through antiangiogenic mechanisms and antipermeability." (PMID 41327436, 2025). "Piezo2 could regulate glioma angiogenesis via Ca2+/Wnt11/β-catenin signaling in endothelial cells." (PMID 27329839, 2016). "Interestingly, Piezo2 knockdown in murine glioma (GL261) cells is sufficient to abrogate these environmental changes, suggesting a potential cross-talk between glioma and endothelial cells that supports tumor growth and reduces apoptosis." (PMID 36158191, 2022).
Gordon syndrome (7 papers, 2015 to 2025). An extremely rare multiple congenital malformation syndrome characterized by congenital contractures of hand and feet with variable degrees of severity of camptodactyly, clubfoot and, less frequently, cleft palate. "Rare PIEZO2 pathogenic variants in humans are associated with neurodevelopmental disorders such as Gordon syndrome and Marden–Walker syndrome as well as distal arthrogryposis." (PMID 40579458, 2025). "Gordon syndrome is associated with allelic variations on the piezo type mechanosensitive ion channel component 2 gene (PIEZO2; MIM 613629)." (PMID 30630514, 2019). "Loss-of-function mutations in human PIEZO2 results in profoundly decreased proprioception leading to ataxia and dysmetria, and gain-of-function mutations of PIEZO2 are directly linked to distal arthrogyposis type 5, Gordon syndrome, and Marden-Walker syndrome." (PMID 35586339, 2022). "Mutations in human PIEZO1 and PIEZO2 can lead to a variety of hereditary diseases, including Piezo1-based dehydrated hereditary stomatocytosis (DHS) and generalized lymphatic dysplasia, and Piezo2-based distal arthrogryposis syndrome, Gordon syndrome and Marden-Walker syndrome." (PMID 33935792, 2021).
Hypertension (6 papers, 2019 to 2025). The presence of chronic increased pressure in the systemic arterial system. "In rats on high fat diet with fructose in the drinking water, there was hypertension associated with decreased Piezo1 mRNA and increased Piezo2 mRNA in the aortic arch." (PMID 40721314, 2025). "The abundance of Piezo1 and Piezo2 mRNAs in nodose ganglia was found to be reduced in rats with spontaneous hypertension or hypertension caused by a nitric oxide synthase inhibitor or angiotensin II." (PMID 40721314, 2025). "Our identification of PIEZO2 gene expression by mRNA and protein analysis in MCs is of particular importance given that high blood pressure represents one of the leading causes of kidney failure and that MCs play a key role in regulating blood flow and surface area of podocytes for filtration." (PMID 31249312, 2019). "In a rat model of hypertension disease, Piezo2 activation was observed in mesangial cells, renin cells, and perivascular mesenchymal cells, implying its contribution to renal fibrosis." (PMID 37958966, 2023). "In mice, double KO of Piezo1 and Piezo2 in the nodose and petrosal sensory ganglia abolished drug-induced baroreflex and aortic depressor nerve activity, with hypertension and increased blood pressure variability." (PMID 33935792, 2021). "Considering the importance of the baroreceptor reflex in cardiovascular disease, targeting Piezo1 and Piezo2 might be a novel strategy for treating hypertension." (PMID 33935792, 2021). "Simultaneously, the absence of Piezo2 in baroreceptor neurons impairs blood pressure regulation, leading to increased blood pressure variability, loss of reflexive heart rate adjustment, a predisposition to hypertension, and causing an imbalance in cardiovascular homeostasis." (PMID 41281194, 2025).
Marden-Walker syndrome (6 papers, 2018 to 2025). Marden-Walker syndrome (MWS) is a malformation syndrome characterized by multiple joint contractures (arthrogryposis), a mask-like face with blepharophimosis, micrognathia, high-arched or cleft palate, low-set ears, decreased muscular bulk, kyphoscoliosis and arachnodactyly. "Mutations in PIEZO2 have been reported in Marden-Walker syndrome, DA3, DA5, and other DAs that involve in sense of touch damage and impaired proprioception." (PMID 30285720, 2018). "DA3 is reported to be caused by mutations in the piezo-type mechanosensitive ion channel component 2 (PIEZO2) gene, which are also likely to be involved in causing DA type 5 and Marden-Walker syndrome." (PMID 32670090, 2020). "The PIEZO2 gene encodes a mechanically activated cation channel, and the mutations of PIEZO2 have been reported in DA3, DA5 and Marden-Walker syndrome MWKS." (PMID 30285720, 2018). "Autosomal dominant PIEZO2 variants are associated with distinct phenotypes, including distal arthrogryposis types 3 and 5 and Marden-Walker syndrome, which do not match the recessive presentation." (PMID 41531622, 2025).
osteoarthritis (6 papers, 2022 to 2025). A noninflammatory degenerative joint disease occurring chiefly in older persons, characterized by degeneration of the articular cartilage, hypertrophy of bone at the margins and changes in the synovial membrane. "Because osteoarthritis pain is associated with weight-bearing activities of daily living, we sought to directly assess the role of Piezo2 in generating pain associated with weight-bearing activities in rodents." (PMID 37120427, 2023). "Our observations support a key role for Piezo2 expressed by nociceptors in mediating mechanical sensitization associated with a mouse model of acute inflammatory knee pain, two mouse models of osteoarthritis, as well as with a model induced by local injection of NGF into the knee over 8 weeks." (PMID 37120427, 2023). "In osteoarthritis, intra-articular or topical therapies are attractive options for local delivery, which could avoid unwanted systemic effects of Piezo2 blockade associated with blocking proprioception." (PMID 37120427, 2023). "Co-expression of Piezo2 and TrkA in human DRGs underscores a conserved NGF-Piezo2 signaling axis implicated in chronic osteoarthritis pain." (PMID 40868398, 2025). "Here we addressed the question if and how chondrocyte expression of the mechanosensitive proteins Piezo1 or Piezo2 controls physiological endochondral ossification and pathological osteoarthritis (OA) development." (PMID 38395992, 2024). "Here, we depleted Piezo2 specifically from nociceptors by using NaV1.8-Cre mice, and used these mice to examine the role of Piezo2 in the development of mechanical sensitization in experimental osteoarthritis." (PMID 37120427, 2023). "Hence, a precise description of the Piezo2 and TrkA signaling axis in the joint is expected to increase our understanding of how pain is produced in osteoarthritis." (PMID 37120427, 2023). "Finally, to investigate whether targeting Piezo2 may represent a suitable strategy for relieving osteoarthritis pain, we used chemogenetics to acutely silence Piezo2 + nerves within the knee joint (heterozygous Piezo2-Cre+/−;Pdifl/+ mice)." (PMID 37120427, 2023). "Hence, Piezo2 may represent a therapeutic target for osteoarthritis pain." (PMID 37120427, 2023). "Therefore, we decided to investigate if Piezo2 contributes to the development of mechanical sensitization associated with two validated models of experimental osteoarthritis (destabilization of the medial meniscus (DMM) surgery and spontaneous osteoarthritis associated with aging)." (PMID 37120427, 2023). "Moreover, injecting CFA into the knee joint resulted in knee swelling and joint pain, whereas the Piezo2 conditional knockout mouse did not exhibit knee swelling or joint pain in the experimental osteoarthritis animal model." (PMID 39372838, 2024). "While nociceptor expression of Piezo2 appears to play an important role in mechanical sensitization in osteoarthritis, inhibition of this pathway did not impact the development of cartilage degeneration, osteophytes, or synovitis after DMM surgery, nor did it prevent age-associated osteoarthritis." (PMID 37120427, 2023).
bladder cancer (5 papers, 2020 to 2025). "Studies have found that Piezo expression in human and mouse bladder cancer, and the expression of Piezo1 and Piezo2 was significantly increased in the tissues." (PMID 38362490, 2024). "By contrast, higher Piezo2 expression was associated with worse outcomes of anti-CTAL4 or anti-PD-L1 treatment in melanoma and bladder cancer." (PMID 35991548, 2022). "Both Piezo1 and Piezo2 mRNA transcripts in bladder cancer tissues were found to be substantially increased in comparison with normal bladder tissues." (PMID 32635333, 2020). "The pathological implications of Piezo1 and Piezo2 in bladder carcinoma in human and mice have been investigated by Etem and colleagues." (PMID 32635333, 2020). "Similarly, in human bladder carcinoma, PIEZO2 expression is significantly higher than in normal bladder tissue, and its expression level increases with tumor grade." (PMID 41327436, 2025).
colorectal cancer (5 papers, 2021 to 2025). A primary or metastatic malignant neoplasm that affects the colon or rectum. "Correspondingly, the proposed quantum mechanical free-energy-stimulated ultrafast proton-coupled tunneling, initiated by Piezo2, seems to be the principal and essential underlying novel oscillatory signaling that could be lost in colorectal cancer onset." (PMID 40806290, 2025).
Ataxia (4 papers, 2022 to 2026). Ataxia refers to impaired coordination of voluntary muscle movement. "Collaborative work from our laboratory also recently established a connection between UBE3A and the mechanosensitive ion channel PIEZO2, leading to the hypothesis that UBE3A might indirectly regulate PIEZO channels, contributing to the both ataxia and hyperphagia in AS." (PMID 37461494, 2023).
distal arthrogryposis (4 papers, 2019 to 2025). A muscle tissue disease characterized by congenital joint contractures of hand and feet. "Slowing inactivation can increase signaling, as shown for human “gain-of-function” PIEZO1 and PIEZO2 mutations leading to dehydrated hereditary stomatocytosis and distal arthrogryposis, respectively." (PMID 41201821, 2025). "Monoallelic gain-of-function variants and biallelic loss-of-function variants in PIEZO2 cause distal arthrogryposis." (PMID 39359478, 2024). "Human PIEZO1 gene mutations resulted in anemia and generalized lymphatic dysplasia, and PIEZO2 gene mutations were proved to cause distal arthrogryposis and other diseases." (PMID 30745454, 2019). "PIEZO2 gene mutations are responsible for distal arthrogryposis and other diseases." (PMID 30745454, 2019).
gastric cancer (4 papers, 2018 to 2025). A primary or metastatic malignant neoplasm involving the stomach. "Surprisingly, hypomethylation of Piezo2 reduced survival time among patients with lung cancer, uveal cancer, stomach cancer, and brain cancer." (PMID 35991548, 2022).
migraine (4 papers, 2022 to 2025). "In migraine models, PIEZO2 contributes to trigeminal hypersensitivity, while PIEZO1 regulates dural endothelial permeability, offering new entry points for treating neurovascular headache syndromes." (PMID 40863236, 2025). "In migraine models, PIEZO1 and PIEZO2 were found to be co-expressed in trigeminal afferents, where they contribute to the mechanosensory amplification of vascular pulsation-induced pain." (PMID 40863236, 2025). "The activation of Piezo2 channels, which are mechanosensitive ion channels, promotes CGRP release from TG neurons during migraine attacks." (PMID 36551174, 2022). "However, unlike in our study, the interaction in migraine occurs in the periphery with highly vascularized dura rather than within the sensory ganglion; the time course is much slower than the clustered firing observed in DRG neurons; and Piezo1 rather than Piezo2 is implicated." (PMID 40154477, 2025).
autoimmune disease (3 papers, 2023). A disorder resulting from loss of function or tissue destruction of an organ or multiple organs, arising from humoral or cellular immune responses of the individual to their own tissue constituents. "The altered expression and dysfunction of the K2P potassium ion channel family may also play a critical role in the pathophysiology of autoimmune diseases, and it is known that both Piezo1 and Piezo2 channels enhance the mechanogating of K2P channels." (PMID 37445856, 2023).